MEST (mesoderm specific transcript)
Diseases named in the same sentence as MEST in open-access papers (continued):
Sharing a sentence is not in itself a finding about the gene and the disease.
autism (2 papers, 2019 to 2020). Persistent deficits in social interaction and communication and interaction as well as a markedly restricted repertoire of activity and interest as well as repetitive patterns of behavior. "MEST is a maternally imprinted gene located in a human autism susceptibility locus; changes in DNA methylation in its promoter affect its expression in the cortex of human, chimpanzee, old world monkey (baboon, rhesus macaque), and new world monkey (marmoset)." (PMID 31428131, 2019).
lung adenocarcinoma (2 papers, 2021 to 2023). A carcinoma that arises from the lung and is characterized by the presence of malignant glandular epithelial cells. "MEST is regulated by genetic imprinting and deregulation of methylation, and its expression has been associated with invasive breast cancer, invasive cervix cancer and the onset of lung adenocarcinoma." (PMID 34454589, 2021).
osteosarcoma (2 papers, 2012 to 2019). A usually aggressive malignant bone-forming mesenchymal neoplasm, predominantly affecting adolescents and young adults. "Chr7q21.3-q32.3 loss comprises the alpha/beta hydrolase MEST (Mesoderm-specific transcript) which has the highest significant negative fold change (log2 Fold Change −9.94; adjusted p value 8.78×10-173) and has been implicated in osteosarcoma oncogenesis." (PMID 31319571, 2019). "Both MEST and NNAT are imprinted genes, and MEST has been shown to be down-regulated in a model of human osteosarcoma, suggesting a role in tumourigenesis." (PMID 23144859, 2012). "MEST and CXCL5 were also shown to be under-expressed in 29/29 osteosarcoma clinical samples, respectively, whereas NNAT was under-expressed in 27/29 samples, based on identical types of microarray data (no methylation data was available)." (PMID 23144859, 2012).
preeclampsia (2 papers, 2017 to 2020). Preeclampsia is a hypertensive disorder of pregnancy that is characterized by new-onset hypertension with proteinuria presenting after 20 weeks of gestation, and depending on mild or severe forms may initially present with severe headache, visual disturbances, and hyperreflexia. "We analyzed the mRNA expression of three imprinting genes SNRPN, PEG10 and MEST in physiological first, second and third trimester groups and placental disorders (preeclampsia and molar pregnancy) and JEG-3 cells (choriocarcinoma cell line)." (PMID 28098215, 2017). "MEST expression was also found to be abnormally lower in preeclamptic maternal blood suggesting the role of overall decrease in MEST levels in development of preeclampsia." (PMID 28098215, 2017). "Decreased expression of MEST as observed in our study, might be contributing to poor angiogenesis observed in preeclampsia, as supported by the role of MEST in trophoblastic angiogenesis." (PMID 28098215, 2017). "Our findings suggest downregulation of placental MEST and NDN expressions among preterm preeclampsia placentas." (PMID 33003346, 2020).
Angelman syndrome (1 paper, 2023). A neurogenetic disorder characterized by severe intellectual deficit and distinct facial dysmorphic features. "Valcarce and colleagues studied the effect of sperm cryopreservation on six genes with roles in fertilization and embryo development (BIK, FSHB, PRM1, ADD1, ARNT and PEG1/MEST) and two genome regions related to Prader–Willi and Angelman syndrome (UBE3A and SNORD116/PWSAS)." (PMID 36902084, 2023).
asthenospermia (1 paper, 2022). "We assessed the DNA methylation patterns of the selected gene regions using the MethylTarget technique, and detected 323 CpG sites, of which only 6 (2 in IGF-2, 1 in KCNQ1, and 3 in MEST) were significantly different between the mild asthenospermia and normozoospermia groups." (PMID 36357889, 2022).
astrocytic tumor (1 paper, 2022). A glial tumor of the brain or spinal cord showing astrocytic differentiation. "EGFR is the most frequently amplified oncogene in astrocytic tumors; expression of genes SRI, NPTX2, MEST, RARRES2, and SEPTIN7 in association with GBM is reported in this study." (PMID 35327982, 2022).
bladder cancer (1 paper, 2022). "For example, LINC00284 targeted MEST to suppress cell proliferation and migration of bladder cancer." (PMID 35281523, 2022).
embryonal cancers (1 paper, 2023). A non-seminomatous malignant germ cell tumor characterized by the presence of large germ cells with abundant cytoplasm resembling epithelial cells, geographic necrosis, high mitotic activity, and pseudoglandular and pseudopapillary structures formation. "A subset (MEST, PLAGL1, PEG3, DLK1, IGF2) showed elevated expression in various embryonal cancers, especially rhabdomyosarcoma, as compared to non-embryonal cancers and normal tissues." (PMID 36437415, 2023).
esophageal cancer (1 paper, 2023). A primary or metastatic malignant neoplasm involving the esophagus. "To examine the clinical significance of MEST dysregulation in esophageal cancer, we determined the expression of MEST in 40 ESCC tissues and paired normal tissues, and the qRT-PCR results showed the upregulation of MEST in the majority of ESCC cases (31/40 cases, 77.5%)." (PMID 37149929, 2023).
Insulin resistance (1 paper, 2023). Increased resistance towards insulin, that is, diminished effectiveness of insulin in reducing blood glucose levels. "Mesoderm-Specific Transcript (MEST) is another notable marker of adipogenesis, upregulation of which has been shown to be associated with increased production of adipocytokines as well as promoting insulin resistance." (PMID 38283397, 2023).
kidney cancer (1 paper, 2024). Primary or metastatic malignant neoplasm involving the kidney. "Several genes showed a low gDS in most kidney cancer cell lines, such as CD82, CD7, MEST, SELP, BMP6, CA2, DNAJC6, and VEPH1." (PMID 38728235, 2024).
leukemia (1 paper, 2021). A malignant (clonal) hematologic disorder, involving hematopoietic stem cells and characterized by the presence of primitive or atypical myeloid or lymphoid cells in the bone marrow and the blood. "In conclusion, MeST has been able to suppress the growth of leukemia cells harboring BCR/ABL." (PMID 34068907, 2021). "We propose that MeST could serve as a plant candidate for leukemia treatment." (PMID 34068907, 2021). "When calculating the SI value of leukemia cells or transfected Ba/F3 cells with the oncogene BCR/ABL, we found that MeST has a high selective effect on abnormal cells." (PMID 34068907, 2021). "In this report, we observed the growth inhibitory effect of MeST on leukemia cells and the induction of apoptosis in CML cells by MeST." (PMID 34068907, 2021).
liver cancer (1 paper, 2023). An epithelial or non-epithelial malignant neoplasm that arises from the liver. "In public databases, high MEST expression was found to be associated with poor prognosis in many cancer types, including brain, cervical, kidney and liver cancers." (PMID 37149929, 2023).
lung neoplasm (1 paper, 2013). A benign or malignant, primary or metastatic neoplasm involving the lungs. "On the other hand, long arm of chromosome 7 possesses imprinted domain in 7q32-qter which including MEST1, MESTIT1, COPG2IT1loci and a group of four carboxypeptidase A (CPA) genes (CPA1, CPA2, CPA4, CPA5), which are seem to be important (mainly MEST) in the initiation of breast and lung neoplasms." (PMID 23288724, 2013).
lymph node metastasis (1 paper, 2023). "Moreover, high MEST expression was significantly associated with lymph node metastasis in cancer patients (Pearson χ2 test, P < 0.001, the student's t test)." (PMID 37149929, 2023).
megakaryoblastic leukemia (1 paper, 2021). "So far, it has been reported that MeST inhibited the growth of the human megakaryoblastic leukemia cell line MEG-01 with an IC50 value of around 80 μg/mL." (PMID 34068907, 2021).
metastatic tumors (1 paper, 2021). "The immunohistochemistry data showed that the majority of the MEST and VCP expression levels in most metastatic tumors was higher than those in the matched primary tumors." (PMID 34560900, 2021).
multiple myeloma (1 paper, 2008). "Interestingly, in the nine multiple myeloma patients overexpressing MEST, 70 genes were significantly upregulated." (PMID 18700954, 2008).
non-small cell lung carcinoma (1 paper, 2025). A group of at least three distinct histological types of lung cancer, including non-small cell squamous cell carcinoma, adenocarcinoma, and large cell carcinoma. "In non-small cell lung carcinoma, VCP interacts with MEST, leading to NF-kB pathway activation, promoting tumor invasion and metastasis." (PMID 39802400, 2025).
omphalocele (1 paper, 2019). Omphalocele is an embryopathy classified in the group of abdominal celosomias and is characterized by a large hernia of the abdominal wall, centered on the umbilical cord, in which the protruding viscera are protected by a sac. "Another case (patient 34) was ascertained with omphalocele, shortened humeri and mesenchymal placenta, and showed LOM of IC2, GRB10 and MEST loci." (PMID 30829192, 2019).
oncocytic thyroid carcinomas (1 paper, 2019). "In oncocytic thyroid carcinomas, ASE analysis of GRB10 and MEST showed a high degree of variability of the distribution of isoforms expressed per allele." (PMID 31093489, 2019).
tumor (26 papers, 2012 to 2026). "Further, the correlation between expression and clinical features was analysed, and indicated that a higher expression level of MEST was associated with greater tumour size and higher Ki67 expression." (PMID 30787268, 2019). "The expression of NAP1L5 and MEST in the tumor regions was decreased, for which the methylation of the originally unmethylated allele was responsible." (PMID 41187747, 2025). "In breast cancer, ZNF57 functions as a tumor suppressor by regulating MEST expression to inhibit the Wnt/β-catenin signaling pathway, thereby affecting tumor cell proliferation." (PMID 40636694, 2025). "Of interest, the same, normally imprinted, MEST SNP (rs10863) also showed biallelic expression in the bulk RNA data of a luminal A tumor (BC01)." (PMID 39766305, 2024). "MEST attracted our attention because it ranked 4th and more importantly, it has been reported to function as both tumor suppressor and oncogene." (PMID 37149929, 2023). "We also aimed to discover small molecules that can inhibit the MEST-mediated signaling pathway and suppress tumor metastasis in vitro and in vivo." (PMID 37149929, 2023). "Deciphering the function of MEST in tumor invasion and metastasis has great functional significance, and elucidating the upstream and downstream mechanisms of MEST will provide mechanistic insight into cancer progression." (PMID 37149929, 2023). "In this study, we identified the MEST protein as an important regulator of tumor metastasis in ESCC." (PMID 37149929, 2023). "The analysis of island 2 showed the highest degree of methylation on island and shore areas (shore 2) in two tumor samples, those that exhibited inhibition in the expression of MEST transcript-001." (PMID 34454589, 2021). "Allelic distributions of the 5 different GRB10 isoforms and the 3 different MEST isoforms in paired normal and tumor samples were compared." (PMID 31093489, 2019). "Additionally, hypomethylation of MEST (Mesoderm-Specific Transcript) leads to its overexpression, enhancing oncogenic signaling and tumor progression." (PMID 40452892, 2025). "Furthermore, silencing of NEAT1 decreased the xenograft tumor growth by decreasing MEST while up-regulating let-7 g and ATGL." (PMID 34416900, 2021). "Decreased methylation in island 1 compared with the control sample agrees with the overexpression of MEST transcript-006 in 50% of the analyzed tumor samples, while the increased methylation on shore island 1 (shore 1) correlates with the inhibition of MEST transcript-007 expression in all tumors." (PMID 34454589, 2021). "Indeed, the chromosome alterations affecting the H19, KCNQ1OT1, PLAGL1 and GNAS DMRs also affected one or more WT driver genes in all analyzed cases, and the chromosome variants affecting the MEST, GRB10 and MEG3 DMRs also affected tumor driver genes in at least 83% of cases." (PMID 33217932, 2020). "Furthermore, overexpression of MEST could restore the tumour-suppressed and the Wnt/β-catenin pathway inactivated effects of ZFP57." (PMID 30787268, 2019). "When taking into account the different tumour subtypes, we detected 24 SNPs (in eight genes: ZDBF2, PEG10, MEST, H19, IGF2, MEG3, ZNF331 and HM13) exhibiting DI in at least one subtype compared to the normal tissue samples." (PMID 30297886, 2018). "Interestingly, expression of mesoderm-specific transcript (Mest)/paternally expressed gene 1 (Peg1), an inhibitory factor of Wnt signaling, was inversely associated with OPN dose in tumors, and it was significantly elevated in tumors compared with adjacent non-tumor parts in Min/OPN(−/−) mice." (PMID 28505114, 2017). "A tissue microarray (TMA) consisting of 242 primary ESCC tissues and 212 nontumor tissues was analyzed, and the expression of MEST was found to be higher in the tumor tissues than in the paired nontumor tissues (P < 0.001, the student's t test)." (PMID 37149929, 2023).
tumor (continued). "Moreover, there was no major downregulation of MEST in this tumor sample (BC05), discarding downregulation as a cause of (higher) biallelic expression (see Section 4)." (PMID 39766305, 2024). "miR-449a was identified as a direct regulator of MEST, and hypermethylation of its promoter led to MEST upregulation, whereas systemically delivered miR-449a mimic could suppress tumor metastasis without overt toxicity." (PMID 37149929, 2023). "To investigate whether MEST mediates the effect of miR-449a on tumor invasion, we further enforced MEST expression in the miR-449a-overexpressing cell lines to establish KYSE150-Luc-LM5-miR-449a-MEST and KYSE410-I6-miR-449a-MEST cells, respectively, with vector as the control." (PMID 37149929, 2023). "In this paper, Migdalska-Sek at al. assessed and compared the methylation level of 8 tumor suppressor genes, ARHI, CDH1, KCNQ1, MEST, p16INK4A, RASSF1A, SLC5A8 and VHL in PTC tumor tissues and matched adjacent noncancerous thyroid tissues." (PMID 25490036, 2014).
cancer (22 papers, 2012 to 2025). A tumor composed of atypical neoplastic, often pleomorphic cells that invade other tissues. "In conclusion, we have identified the MEST-PURA-SRCIN1/RASAL1-ERK-snail signaling cascade as a key mechanism underlying cancer metastasis." (PMID 37149929, 2023). "High MEST expression was associated with poor patient survival and promoted cancer invasion and metastasis in ESCC." (PMID 37149929, 2023). "We identified the MEST-PURA-SRCIN1/RASAL1-ERK-snail signaling cascade as an important mechanism underlying cancer metastasis." (PMID 37149929, 2023). "To reveal the upstream regulatory mechanisms of MEST, we initiated a screening for candidate miRNAs that can directly target MEST to regulate cancer metastasis." (PMID 37149929, 2023). "The Western blot results confirmed that overexpression of MEST enhanced ERK phosphorylationing the role of MEST in cancer metastasis, RNA sequencing (RNA-seq) was used to compare the gene profiles between MEST-o-I6 cells." (PMID 37149929, 2023). "MEST is an attractive cancer target because it is upregulated in the majority of ESCC tumors examined, it is expressed at a low level in normal tissues, and its suppression has a minimal effect on normal cells." (PMID 37149929, 2023). "To examine the biological function of MEST in cancer, we established MEST-overexpressing stable cell lines (from A549 and H1299 cells) and MEST-knockdown cell lines (from A549-i8 and H1299-i8 cells)." (PMID 34560900, 2021). "It would be interesting to further identify the upstream regulation of MEST to ask how cancer cell acquires MEST expression." (PMID 34560900, 2021). "In conjunction, a previously conducted study has displayed that the knockdown of MEST reduces cell proliferation whereas promoting the apoptosis of cancer cells." (PMID 34416900, 2021). "Western blot analysis confirmed increased MEST protein expression in both LM5 and I6 cells to a level observed in the parental cells, suggesting that MEST may be a key regulator of cancer metastasis." (PMID 37149929, 2023). "We aimed to identify small molecules that could directly target the MEST protein and simultaneously suppress cancer invasion and metastasis." (PMID 37149929, 2023). "However, the diverse functions and mechanisms of MEST in ESCC proliferation as well as other cancers need further studies." (PMID 37149929, 2023). "Boyden chamber assays and Western blot analysis showed that the inhibitory effect of miR-449a on cancer cell invasion could be abrogated by overexpression of MEST." (PMID 37149929, 2023). "Taken together, these results suggest that MEST may function as a key mediator in the suppressive effect of miR-449a in cancer invasion and metastasis." (PMID 37149929, 2023). "Blockade of MEST-PURA interaction has therapeutic potential in management of cancer metastasis." (PMID 37149929, 2023). "Taken together, these results suggest that MEST may be a useful biomarker for cancer diagnosis and prognosis." (PMID 37149929, 2023). "Blockade of MEST-PURA interaction has therapeutic potential in the management of cancer metastasis." (PMID 37149929, 2023). "Collectively, these results illustrate that MEST may play a functional role in regulating cancer metastasis." (PMID 34560900, 2021). "Upregulation of MEST expression via LOI is also observed in other cancers." (PMID 32697014, 2020). "MEST is already known to show DI in varying cancers, including breast cancer." (PMID 30297886, 2018). "The imprinting of MEST is known to be disrupted in model cancer cell lines; HeLa and MDA-MB-231-BAG cell lines were observed to have predominantly hypermethylated epialleles at this locus and is in keeping with publically available datasets with these cell lines found on ENCODE." (PMID 26911705, 2016).
cancer (continued). "More importantly, unlike that in PURA-expressing cell lines, there was no change in the invasive and metastatic potential upon overexpression of MEST in PURA-deficient ESCC cells, and the promoting effects of MEST in cancer invasion and metastasis could be restored by re-overexpression of PURA." (PMID 37149929, 2023). "Up to now, the biological function of MEST in cancer is unknown." (PMID 37149929, 2023). "By analyzing scRNA-seq data from 486 cancer cells across subtypes, we identified multiple SNPs in imprinted genes, including HM13, MEST (PEG1), SNHG14 and PEG10, showing consistent biallelic expression." (PMID 39766305, 2024). "Taken together, our results demonstrate that MEST regulates SRCIN1/RASAL1-ERK-snail signaling and cancer metastasis in a PURA-dependent manner." (PMID 37149929, 2023). "The present study provides evidence suggesting that overexpression of MEST is a common event in ESCC, and it highlights the role of MEST as a potential driver of cancer metastasis." (PMID 37149929, 2023). "First, we targeted the following loci given the initial observation from TCGA: five imprinted domains (PEG3, H19/IGF2, DLK1/GTL2, MEST, GNAS) and four cancer genes (APC, MLL3, MGMT, ELF3)." (PMID 26338779, 2015). "MEST is a cancer-related maternal imprinted gene, which is essential for normal early embryonic progression." (PMID 34416900, 2021). "In summary, a series of DNA methylation surveys revealed that a relatively large fraction of imprinted genes are epigenetically affected in human cancers, and also that this epigenetic instability is particularly pronounced in a subset of imprinted genes, such as PEG3, IGF2, DLK1, MEST and GNAS." (PMID 26338779, 2015). "However, the role of MEST in cancer has not been reported till now." (PMID 37149929, 2023).